PHC2 (polyhomeotic homolog 2)
Description:
Component of a Polycomb group (PcG) multiprotein PRC1-like complex, a complex class required to maintain the transcriptionally repressive state of many genes, including Hox genes, throughout development. PcG PRC1 complex acts via chromatin remodeling and modification of histones; it mediates monoubiquitination of histone H2A 'Lys-119', rendering chromatin heritably changed in its expressibility.
Synonyms: hPH2; EDR2; PH2
Tractability: PROTAC: UniProt records ubiquitination sites on it; ubiquitination databases record sites on it; its protein half-life has been measured.
Gene: Protein-coding gene on chromosome 1 (33,323,623 to 33,431,095, reverse strand). Ensembl gene ENSG00000134686.
Subcellular location: Nucleus
Subcellular location (Human Protein Atlas): Nucleoplasm
Pathways (Reactome):
Metabolism of proteins: SUMOylation of DNA damage response and repair proteins; SUMOylation of DNA methylation proteins; SUMOylation of RNA binding proteins; SUMOylation of chromatin organization proteins; SUMOylation of transcription cofactors
Cellular responses to stimuli: Oxidative Stress Induced Senescence
Developmental Biology: Differentiation of naive CD4+ T cells to T helper 2 cells (Th2 cells)
Gene expression (Transcription): RUNX1 interacts with co-factors whose precise effect on RUNX1 targets is not known
Signal Transduction: Regulation of PTEN gene transcription
Gene Ontology:
Molecular function: identical protein binding; protein binding; chromatin binding; histone binding; zinc ion binding
Biological process: heterochromatin formation; negative regulation of DNA-templated transcription
Cellular component: nucleoplasm; nucleus; PcG protein complex; PRC1 complex; chromatin
Genetic constraint (gnomAD): Loss-of-function variants: 28 observed, 78.09 expected, observed/expected ratio (o/e) 0.36, 90% interval 0.26 to 0.49. The upper end of that interval is the gene's LOEUF score, 0.49, which puts it in group 2 of 6, group 1 being the genes least tolerant of losing a copy. Missense variants: 809 observed, 1,093.9 expected, observed/expected ratio (o/e) 0.74, 90% interval 0.7 to 0.78. Synonymous variants: 416 observed, 447.43 expected, observed/expected ratio (o/e) 0.93, 90% interval 0.86 to 1.01.
Homologues: Orthologues: chimpanzee PHC2 (99% identical), macaque PHC2 (98% identical), pig PHC2 (93% identical), dog PHC2 (92% identical), guinea pig PHC2 (91% identical), rabbit PHC2 (91% identical), rat Phc2 (88% identical), mouse Phc2 (87% identical), tropical clawed frog phc2 (51% identical), Drosophila melanogaster l(3)mbt (14% identical), Drosophila melanogaster Scm (10% identical), Caenorhabditis elegans lin-61 (7% identical), and 2 more. Paralogues in human: PHC3 (42% identical), PHC1 (35% identical), SFMBT1 (13% identical), SAMD11 (12% identical), SFMBT2 (12% identical), SCMH1 (11% identical), L3MBTL4 (11% identical), SCML2 (11% identical), L3MBTL3 (10% identical), L3MBTL1 (10% identical), SAMD7 (8% identical), L3MBTL2 (8% identical), and 6 more.
Diseases named in the same sentence as PHC2 in open-access papers:
PHC2 is named in the same sentence as 11 diseases in open-access papers, as found by Europe PMC text mining. Sharing a sentence is not in itself a finding about the gene and the disease. The quoted sentences say what the papers report.
cervical cancer (1 paper, 2025). A primary or metastatic malignant neoplasm involving the cervix. "We found that CBX2, CBX4, and CBX8 presented notably increased expression, whereas PHC2, CBX6, and CBX7 presented decreased expression in cervical cancers." (PMID 39793896, 2025).
glioma (1 paper, 2013). A benign or malignant brain and spinal cord tumor that arises from glial cells (astrocytes, oligodendrocytes, ependymal cells). "However, in a cohort which includes low grade gliomas, significant survival benefits were observed for patients with low EZH2, PHF19, CBX8 and PHC2 expression, and high CBX7, CBX6, RYBP and EZH1 expression." (PMID 24260522, 2013).
Immunodeficiency (1 paper, 2023). Failure of the immune system to protect the body adequately from infection, due to the absence or insufficiency of some component process or substance. "It has also been shown that PHC2 can bind to the Vcam1 locus and act to reduce systemic immunodeficiency." (PMID 37138862, 2023).
mastitis (1 paper, 2020). Inflammation of breast tissue during lactation or postpartum due to an obstructed duct or infection. "Comparison with indigenous pigs showed genes that were associated with mastitis resistance (ARHGAP39, ARPC4, PHC2, and BCL2L15) and hair follicle development (FOXN1)." (PMID 32457791, 2020).
prostate carcinoma (1 paper, 2023). A carcinoma that arises from epithelial cells of the prostate gland. "This indicates that PHC2 methylation is associated with the occurrence and progress of prostate cancer." (PMID 37752559, 2023). "In an epigenetic study of prostate cancer cells, it was found that R1881 treated cells had higher PHC2 methylation." (PMID 37752559, 2023).
infection (6 papers, 2017 to 2024). The state of being infected such as from the introduction of a foreign agent such as serum, vaccine, antigenic substance or organism. "Gene expression differences for Arl2bp and Phc2 were confirmed by RT-PCR on MLN samples at day 5 of infection of wild-type and MIF-deficient mice." (PMID 31708913, 2019). "Six UPS factors were discovered to be essential for infection with the three viruses (DCAF12L, DDB1, FBXL19, OTUD6A, PAN2, and PHC2)." (PMID 29202037, 2017).
cancer (2 papers, 2010 to 2020). A tumor composed of atypical neoplastic, often pleomorphic cells that invade other tissues. "Interestingly, in Normal tissues from 18 non-cancer patients, we found that transcription of Cbx7 was positively correlated with those of Ring1, Bmi1, Mel18, and Phc2, but not with those of Cbx8 and Ezh2 (Ps<0.01)." (PMID 21060834, 2010).
tumor (2 papers, 2020 to 2023). "In the TCGA-HCC dataset, 13 genes were identified with significant correlation with SAMD13 from the tumor group only and a total of six genes including FOXM1, JUN, JARID2, BRE, BUB1B, and PHC2 were shown to significantly predict poor overall survival in log-rank tests in HCC." (PMID 37968735, 2023).
PHC2 also shares sentences with these, for which no sentence is quoted: cleft lip (1 paper); hypospadias (1); neuropathies (1).